CTSC (cathepsin C)
Diseases named in the same sentence as CTSC in open-access papers (continued):
Sharing a sentence is not in itself a finding about the gene and the disease.
glioma (continued). "To further explore whether high CTSC expression predicts adverse prognosis in patients with glioma, we analyzed clinical samples based from the CGGA RNA-seq, CGGA microarray, and TCGA RNA-seq databases and plotted receiver operating characteristic (ROC) curves." (PMID 35109832, 2022). "Hence, we speculated that there was a close correlation between high CTSC expression and malignant progression of glioma." (PMID 35109832, 2022). "And we proved piperlongumine and scopoletin could inhibit CTSC expression in glioma cells." (PMID 35109832, 2022). "Moreover, we screened and verified two small-molecule drugs that inhibited CTSC expression, which may expand the treatment of glioma." (PMID 35109832, 2022). "Therefore, we also performed relevant experiments to identify drugs that could inhibit CTSC expression and thereby possibly attenuate glioma growth." (PMID 35109832, 2022). "We explored the expression pattern of CTSC in human tumors based on the GEPIA database and found that CTSC was highly expressed in many tumors (red marked), including GBM and low-grade glioma." (PMID 35109832, 2022). "Our analyses showed that the expression of CTSC in glioma was higher than that in non-cancerous cells." (PMID 35109832, 2022). "To further explore the specific mechanism by which CTSC affects the malignant progression of glioma, we used GSEA to identify the signaling pathways in which CTSC might participate." (PMID 35109832, 2022). "We found that CTSC participated in the Toll-like receptor signaling pathway, cancer pathways, and ECM receptor interaction signaling pathway, which are all well-known pathways regulating the process of glioma." (PMID 35109832, 2022). "Our study at the genetic level found that SCO targeted and inhibited CTSC expression in glioma, indicating that SCO might be a promising antitumor agent for the treatment of glioma." (PMID 35109832, 2022). "Previous studies have reported the role of CTSC in some cancers, but its relationship with aging and gliomas is not clear." (PMID 33946049, 2021). "The expression of CTSC in glioma was higher than that in no-cancerous cells." (PMID 38767825, 2024). "However, because the mechanism by which CTSC expression affects the malignant process of glioma is unknown, we conducted GSEA to identify the signaling regulatory pathways related to CTSC expression." (PMID 35109832, 2022). "However, whether CTSC is involved in the pathological process of glioma has not yet been reported." (PMID 35109832, 2022).
autoimmune disease (5 papers, 2011 to 2025). A disorder resulting from loss of function or tissue destruction of an organ or multiple organs, arising from humoral or cellular immune responses of the individual to their own tissue constituents. "Almost all variants identified (ZNF365, TNFSF4, NAB1, IKZF4-ERBB3, CTSC, DENND1B, SIRPG, and PRF1) are the same or strongly linked with markers associated with other autoimmune diseases." (PMID 37188663, 2023). "Notably, pharmaceutical inhibition of cathepsin C has also been shown to suppress NE and PR3 activity in models of vasculitis, resulting in reduced NET burden and decreased disease severity in MPO-ANCA-associated vasculitis (MPO-AAV), a neutrophil-driven autoimmune disorder." (PMID 41303697, 2025).
diabetes (5 papers, 2019 to 2023). "Previous meta-analysis of GWAS demonstrated that variation of RAB38/CTSC was highly associated with UACR of European ancestry with diabetes." (PMID 33096837, 2020). "In addition, variants in HS6ST1 and near RAB38/CTSC were implicated in albuminuria in patients with diabetes." (PMID 30900988, 2019). "In diabetes, cathepsin C has only been studied for its differential expression and activity in immune cells." (PMID 34828301, 2021).
prostate carcinoma (5 papers, 2006 to 2023). A carcinoma that arises from epithelial cells of the prostate gland. "Among others, keratin 81, CrkII, IL-1β, and cathepsin C were identified as proteins directly or indirectly targeted by CA2-2 in human prostate cancer cells." (PMID 38248645, 2023).
rheumatoid arthritis (5 papers, 2011 to 2025). A chronic, systemic autoimmune disorder characterized by inflammation in the synovial membranes and articular surfaces. "Nowadays, cathepsin C has received increasing attention due to its biological roles in various systemic diseases, such as tumor, osteoporosis and rheumatoid arthritis." (PMID 35037834, 2022). "Therefore, CTSC inhibitors have been developed for the treatment of non-cystic fibrosis bronchiectasis (NCFBE), chronic obstructive pulmonary disease (COPD), rheumatoid arthritis (RA), inflammatory bowel disease (IBD), and anti-neutrophil cytoplasmic antibody-associated vasculitis." (PMID 41226133, 2025).
Sepsis (5 papers, 2016 to 2025). Sepsis is defined as life-threatening organ dysfunction caused by a dysregulated host response to infection. "Antioxidants, such as N-acetylcysteine (NAC) and diphenyleneiodonium (DPI), along with cathepsin C (CTSC) inhibitors like AZD7986, reduce ROS-driven NET formation, improving outcomes in models of sepsis and cancer metastasis." (PMID 40442839, 2025). "However, there were no changes in the expression levels of CTSC, CTSG, PRTN3 and ELANE in neutrophils during sepsis compared to those from healthy controls." (PMID 33868254, 2021).
squamous cell carcinoma (5 papers, 2021 to 2024). A carcinoma arising from squamous epithelial cells. "CTSC is a lysosomal cysteine protease of the papain family and is correlated with the development of squamous cell carcinoma." (PMID 38903709, 2024). "Increased levels of enzymatically active CTSC contributes to squamous cell carcinoma growth via regulating infiltrating immune cells in neoplastic skin, development of angiogenic vasculature, and squamous cell carcinoma growth." (PMID 34923982, 2021). "Moreover, CTSC has been shown to control the infiltration of immune cells in the skin tumors and promote angiogenesis in squamous cell carcinoma." (PMID 35109832, 2022).
atherosclerosis (4 papers, 2021 to 2025). A disease characterized by the build-up of fatty material and calcium deposition in the arterial wall resulting in partial or complete occlusion of the arterial lumen. "In conclusion, a Venn diagram illustrated TGFBI, GMFG, and CTSC as key genes associated with both atherosclerosis and disulfidptosis." (PMID 40299531, 2025). "Models of atherosclerosis were developed both in vivo and in vitro to elucidate the role of the characteristic gene CTSC." (PMID 40299531, 2025). "Flow cytometry analysis further illustrated that CTSC knockdown markedly diminished apoptosis in SMCs within the atherosclerosis model." (PMID 40299531, 2025). "In the smooth muscle cell (SMC)-focused in vitro model of atherosclerosis, RT-qPCR analysis demonstrated that the expression levels of CTSC, TGFBI, and GMFG were significantly elevated compared to those in the control group." (PMID 40299531, 2025). "Through single-cell RNA sequencing and machine learning, we pinpointed CTSC, TGFBI, and GMFG as key biomarkers for atherosclerosis risk stratification." (PMID 40299531, 2025). "Machine learning-based techniques, including LASSO, Boruta, Support Vector Machine, and Random Forest, were employed to specifically identify CTSC, TGFBI, and GMFG as potential diagnostic biomarkers associated with SMC activity in atherosclerosis." (PMID 40299531, 2025). "Hematoxylin and eosin (HE) staining revealed that CTSC knockdown effectively reduced plaque area in the rat atherosclerosis model." (PMID 40299531, 2025). "This was to explore the mechanism behind the involvement of CTSC in the development of atherosclerosis by regulating macrophage polarization and promoting inflammatory response." (PMID 34737793, 2021). "Further, it was found that p-p38 (downstream effector molecule) was significantly increased with an increase in CTSC in both atherosclerosis and SCD groups, but a higher expression was found in the SCD group." (PMID 34737793, 2021). "It was revealed that the positive expression of CTSC was mainly localized in the cytoplasm of foam cells, higher in the atherosclerosis and SCD groups compared with the control (p < 0.05)." (PMID 34737793, 2021). "Although the specific contribution of CTSC to atherosclerosis remains unclear at present, insights from its role in the tumor microenvironment provide valuable direction." (PMID 40299531, 2025). "Notably, CTSC knockdown significantly enhanced cell viability in the SMC-based atherosclerosis model and decreased LDH release." (PMID 40299531, 2025). "Furthermore, ROS fluorescence detection indicated that CTSC knockdown led to a reduction in ROS expression levels in the SMC-based atherosclerosis model when compared to the empty viral vector control group." (PMID 40299531, 2025). "Besides CTSK, other members of the cathepsin family, including cathepsin B (CTSB) 52, cathepsin S (CTSS) 53, cathepsin L (CTSL) 54, and cathepsin C (CTSC) 55, also play a critical role in the development of atherosclerosis." (PMID 35673565, 2022). "Besides, SCD cases had even higher positive expression of CTSC compared with atherosclerosis cases (p < 0.05)." (PMID 34737793, 2021). "In addition, CTSC contains a signal peptide which can be secreted by a variety of cells, but the role of secreted CTSC in the development of atherosclerosis is still a mystery that requires further study." (PMID 34737793, 2021). "Based on the IogFc values, we observed that the differential expressions of CTSS, CTSB, and CTSC were the highest in atherosclerotic plaques and the expressions were positively expressed in advanced plaques, indicating a positive trend of promoting atherosclerosis." (PMID 35186462, 2022). "CTSS, CTSC, and CTSB are the main target molecules in the CTS family that are involved in atherosclerosis." (PMID 35186462, 2022).
Hyperkeratosis (4 papers, 2020 to 2024). Hyperkeratosis is a histopathological term defining a thickened stratum corneum and may be present in many different skin conditions, with many possible overlaps. "In addition to activation of immune cells, the proteolytic activity of CTSC has also been proposed to play a role in epithelial differentiation and desquamation, likely explaining the skin phenotype that is dominated by palmoplantar hyperkeratosis." (PMID 32625202, 2020).
periodontal disease (4 papers, 2013 to 2017). "The aim of the present study was to investigate gingival crevicular fluid (GCF) proteinase 3 and cathepsin C levels in periodontal diseases." (PMID 24949444, 2014). "Further studies are needed to evaluate the activity of cathepsin C and proteinase 3 enzymes in different periodontal diseases as well as after periodontal treatment." (PMID 24949444, 2014). "There are limited numbers of studies investigating the roles of proteinase 3 and cathepsin C in the pathogenesis of periodontal diseases." (PMID 24949444, 2014). "In order to test this hypothesis, we aimed to determine the GCF levels of proteinase 3 and cathepsin C in patients with different periodontal diseases." (PMID 24949444, 2014). "However, cathepsin C in GCF does not seem to have an effect on the pathogenesis of periodontal diseases." (PMID 24949444, 2014).
colon cancer (3 papers, 2023 to 2026). "Using the TNMplot database, we observed that tumoral CTSC expression was significantly higher than adjacent normal tissues in patients with breast and colon cancer." (PMID 41480760, 2026). "Obviously, patients with higher CTSC level exhibited significantly shorter survival, validated by 2 independent cohorts of patients with breast and colon cancer who had received chemotherapy." (PMID 41480760, 2026). "In addition, it was confirmed that CTSC was hardly expressed in normal cells, but significantly expressed in colon cancer cell lines." (PMID 36831614, 2023). "CTSC expression was higher in the colon cancer samples than in normal samples." (PMID 36831614, 2023). "A decrease in CTSC expression reduced spheroid viability after 5 days in colon cancer cells." (PMID 36831614, 2023). "In conclusion, we have developed a gene expression score, based on ZNF697, CTSC, SNORA2B, and OXLD1, that effectively stratifies patients with stage II colon cancer into low and high‐risk groups, facilitating the identification of patients who may benefit from adjuvant chemotherapy." (PMID 40478186, 2025). "A dichotomized score, derived from the combined expression of four RNAs (ZNF697, SNORA2B, CTSC and OXLD1), effectively predicted TTR in stage II colon cancer patients." (PMID 40478186, 2025).
depression (3 papers, 2020 to 2025). "Depression-like behavior in CTSC overexpression was also shown to be associated with increased neuroinflammation and decreased 5-hydroxytryptamin (serotonin) levels." (PMID 32793006, 2020). "Mice with CTSC overexpression exhibit heightened anxiety and depression under both acute and chronic stress conditions." (PMID 41463031, 2025). "In contrast, cathepsin C aggravates neuroinflammation involved in behavioural and neurochemical disturbances in acute and chronic stress-induced murine models of depression." (PMID 37958596, 2023). "Behavioral testing in these mice revealed that an overexpression of CTSC promoted the induction of depression-like behavior whilst CTSC knock-down was protective against this behavior." (PMID 32793006, 2020). "Cathepsin C (CTSC) has also been suggested to play a critical role in the development of depression." (PMID 32793006, 2020). "Conversely, knockdown of CTSC has been shown to prevent these behaviors, suggesting that CTSC inhibition could be a potential therapeutic strategy for alleviating depression." (PMID 41463031, 2025). "In contrast, cathepsin C knockdown partially prevents inflammation, which may help alleviate the symptoms of depression in mice." (PMID 37958596, 2023). "For example, overexpression of CTSC in the brain resulted in a depression-like phenotype." (PMID 32793006, 2020).
liver cancer (3 papers, 2023 to 2025). An epithelial or non-epithelial malignant neoplasm that arises from the liver. "Compared with the adjacent tumor tissue and most liver cancer cells lines, a significant increase expression of G6PD, CDCA8, and CTSC in HCC tissues and liver cancer cells was observed, whereas CXCL9 was significant downregulated." (PMID 38742112, 2024).
lung disease (3 papers, 2023 to 2026). "CTSC is mainly linked to NSP-mediated lung diseases, which include ARDS, CF, and COPD, due to its role in NSP activation." (PMID 38791530, 2024). "Because of these pro-inflammatory links, targeting CTSC activity using inhibitors has been investigated in both animal models and clinical trials regarding lung disease." (PMID 38791530, 2024).
pancreatic cancer (3 papers, 2021 to 2025). "In contrast, CTSC was a risk factor for pancreatic cancer via Mendelian randomization, with a significant positive correlation with CHST11 in TCGA (R = 0.44) and higher expression in naïve T cell_pos than in naïve T cell_neg." (PMID 41346619, 2025). "Results showed that CHST11 had high overall expression in pancreatic cancer tissues and shared significant co-expression regions with CTSC in spatial distribution." (PMID 41346619, 2025). "Mendelian randomization identified CTSC as an adverse factor for pancreatic cancer; TCGA data showed CTSC was significantly positively correlated with CHST11 and associated with poor prognosis." (PMID 41346619, 2025). "Spatial transcriptomics analysis showed high CHST11 expression in Ep_KRT6A and significant co-localization between CHST11 and CTSC, suggesting they may synergistically promote pancreatic cancer progression." (PMID 41346619, 2025). "Meanwhile, CHST11 and CTSC may synergistically promote pancreatic cancer progression." (PMID 41346619, 2025).
preeclampsia (3 papers, 2022 to 2025). Preeclampsia is a hypertensive disorder of pregnancy that is characterized by new-onset hypertension with proteinuria presenting after 20 weeks of gestation, and depending on mild or severe forms may initially present with severe headache, visual disturbances, and hyperreflexia. "Cathepsin C and cathepsin D are risk factors for preeclampsia: a case control study." (PMID 37794357, 2023). "Using an L-NAME-induced rat model of preeclampsia, we administered SCFA supplements and performed rescue experiments via forced cathepsin C overexpression to establish causality." (PMID 41333475, 2025). "Our study elucidates a novel immunological pathway in preeclampsia (PE) pathogenesis, centering on the “gut microbiota–SCFAs–cathepsin C–macrophage polarization” axis." (PMID 41333475, 2025). "This unexpected discrepancy, therefore, helps us more precisely define the principal role of Cathepsin C in the pathological process of preeclampsia." (PMID 41333475, 2025). "This study provides for the first time the changes in serum and placental levels of cathepsin C and cathepsin D in nonpregnant subjects, in all stages of pregnancy, and in patients with preeclampsia at the same time, and explores their significance." (PMID 37794357, 2023).
prepubertal periodontitis (3 papers, 2010 to 2022). "Mutations in cathepsin C gene were found to be related to prepubertal periodontitis." (PMID 24949444, 2014).
viral infection (3 papers, 2019 to 2023). "The club cells also expressed high levels of protease-related genes (PRSS23, CTSC), that together with anti-proteases, are important for the susceptibility to viral infection." (PMID 32727470, 2020). "Albeit cathepsin C has an essential role in the in vivo activation of granzymes A and B, residual granzyme B activity is sufficient to combat viral infection in cathepsin C null mice." (PMID 31555270, 2019).
acute kidney injury (2 papers, 2022 to 2024). Sudden and sustained deterioration of the kidney function characterized by decreased glomerular filtration rate, increased serum creatinine or oliguria. "Further analyses that included vancomycin as an additional potential stressor revealed a common match for genes encoding cathepsin A, cathepsin C, cathepsin D and cathepsin S and an association of cathepsins with the lysosomal pathway, kidney disease and acute kidney injury." (PMID 35516525, 2022).
apical periodontitis (2 papers, 2022 to 2023). "A previous study carried out by our group used micro-CT to compare the volume of apical periodontitis-induced bone loss in cathepsin C (Cat C) knock-down (KD) mice and normal mice, but the focus of the present study was not to detect bone loss." (PMID 35953782, 2022). "It has been demonstrated that cathepsin C refers to the overall progression of periapical periodontitis." (PMID 37334378, 2023). "Besides, the mRNA and protein levels of cathepsin C were significantly increased in acute periapical periodontitis." (PMID 37334378, 2023).
Arthritis (2 papers, 2023 to 2025). Inflammation of a joint. "In addition, the potential of CTSC as a therapeutic target has been evaluated in various arthritis models." (PMID 41226133, 2025). "In the adjuvant-induced arthritis model, high-dose marrubiin (IC50 = 60 mg/kg) exerted a therapeutic effect by reducing the activities of CTSC and NSPs." (PMID 41226133, 2025).
breast tumor (2 papers, 2023 to 2026). "The clinical relevance of these findings was highlighted by elevated neutrophil infiltration and NET formation in human lung metastasis as compared with the primary breast tumor and a positive correlation of these factors with cathepsin C expression." (PMID 36002710, 2023).